DEFB131B (defensin beta 131B)
Description:
Has antibacterial activity.
Gene: Protein-coding gene on chromosome 11 (71,878,453 to 71,884,561, forward strand). Ensembl gene ENSG00000225805.
Subcellular location: Secreted
Gene Ontology:
Biological process: innate immune response
Cellular component: extracellular region
Genetic constraint (gnomAD): Loss-of-function variants: 3 observed, 3.48 expected, observed/expected ratio (o/e) 0.86, 90% interval 0.38 to 1.8. That is too few expected variants to judge how well the gene tolerates losing a copy. Missense variants: 77 observed, 78.93 expected, observed/expected ratio (o/e) 0.98, 90% interval 0.81 to 1.18. Synonymous variants: 26 observed, 26.16 expected, observed/expected ratio (o/e) 0.99, 90% interval 0.73 to 1.38.
Homologues: Orthologues: chimpanzee DEFB131B (100% identical), dog CBD131 (54% identical), rat Defb43 (53% identical), mouse Defb43 (51% identical). Paralogues in human: DEFB131A (94% identical), DEFB129 (27% identical), DEFB123 (26% identical), DEFB128 (26% identical), DEFB135 (26% identical), DEFB134 (24% identical), DEFB108B (23% identical), DEFB115 (23% identical), DEFB119 (23% identical), DEFB124 (23% identical), DEFB132 (23% identical), DEFB108C (21% identical), and 7 more.